CTXN3 (cortexin 3)
Synonyms: KABE
Tractability: Antibody: UniProt predicts a signal peptide or a membrane-spanning region.
Gene: Protein-coding gene on chromosome 5 (127,649,082 to 127,658,630, forward strand). Ensembl gene ENSG00000205279.
Subcellular location: Membrane
Subcellular location (Human Protein Atlas): End piece; Principal piece
Gene Ontology:
Molecular function: protein binding
Cellular component: membrane
Genetic constraint (gnomAD): Loss-of-function variants: 4 observed, 4.48 expected, observed/expected ratio (o/e) 0.89, 90% interval 0.43 to 1.77. That is too few expected variants to judge how well the gene tolerates losing a copy. Missense variants: 79 observed, 91.36 expected, observed/expected ratio (o/e) 0.86, 90% interval 0.72 to 1.04. Synonymous variants: 42 observed, 36.24 expected, observed/expected ratio (o/e) 1.16, 90% interval 0.9 to 1.5.
Homologues: Orthologues: chimpanzee CTXN3 (98% identical), guinea pig CTXN3 (94% identical), dog CTXN3 (93% identical), pig CTXN3 (93% identical), rabbit CTXN3 (93% identical), mouse Ctxn3 (91% identical), rat Ctxn3 (91% identical), tropical clawed frog ctxn3 (73% identical), zebrafish ctxn3 (69% identical). Paralogues in human: CTXN2 (51% identical), CTXN1 (43% identical).
Diseases named in the same sentence as CTXN3 in open-access papers:
CTXN3 is named in the same sentence as 10 diseases in open-access papers, as found by Europe PMC text mining. Sharing a sentence is not in itself a finding about the gene and the disease. The quoted sentences say what the papers report.
schizophrenia (3 papers, 2012 to 2020). A major psychotic disorder characterized by abnormalities in the perception or expression of reality. "CTXN3 resides in a genomic region (5q21-34) known to be associated with schizophrenia and encodes a protein cortexin 3 which is highly enriched in brain." (PMID 25889058, 2015). "There have been two previous attempts to establish an association between polymorphisms of CTXN3 gene and schizophrenia." (PMID 25889058, 2015). "We found a statistically significant association between schizophrenia and rs6595788 polymorphism of CTXN3 gene." (PMID 25889058, 2015). "We have found a statistically significant association between rs6595788 polymorphism of CTXN3 gene and the risk of schizophrenia; the presence of AG genotype increased the risk 1.5-fold." (PMID 25889058, 2015). "DISC1 (disrupted-in-schizophrenia 1) has been studied extensively in relation to mental disease while CTXN3, has only recently emerged as a potential “candidate” gene in schizophrenia." (PMID 25889058, 2015). "In conclusion, we report a strong association between schizophrenia and a single nucleotide polymorphism in the CTXN3 gene (cortexin 3) in an ethnically homogenous group of male patients." (PMID 25889058, 2015). "We first tested the associations between the GWAS-discovered SNPs that located in the intergenic of CTXN3SLC12A2 region, 3'-UTR and intronic of CTXN3 gene with schizophrenia in Thai population." (PMID 22643131, 2012). "Further study, it would be of interest to identify genetic variation around these SNPs affecting the expression pattern of the CTXN3 and SLC12A2 genes and test the association with risk for schizophrenia." (PMID 22643131, 2012). "This study shows that two SNPs in intergenic of the CTXN3 and SLC12A2 genes, rs245178 and rs698172, are associated with risk of schizophrenia in Thai population." (PMID 22643131, 2012). "We now report on the rs6595788 polymorphism of CTXN3 gene and the rs17817356, rs821597, rs9661837, rs980989 and rs3737597 polymorphisms of DISC1 gene and discuss them as possible risk factors for pathophysiology of schizophrenia in a group of male patients and controls." (PMID 25889058, 2015). "Taking into account the developmental hypothesis of schizophrenia, we conjecture that any genetic variations in the CTXN3 gene affecting expression and/or characteristic of cortexin 3 protein would have a potential to contribute to the aetiology of complex mental diseases." (PMID 25889058, 2015). "Both CTXN3 and SLC12A2 are indicated to play a role in normal brain function, in addition, the CTXN3-SLC12A2 region is considered as the second most important region linked to schizophrenia in the meta-analysis, therefore, they may be involved in schizophrenia pathogenesis." (PMID 22643131, 2012). "Changes in cortexin 3/DISC1/APP interactions could, therefore, result in altered expression and distribution of NMDA receptors as has been observed in schizophrenia (review:)." (PMID 25889058, 2015). "Further study is required for clarification the role of genetic variation around these SNPs in expression pattern of the CTXN3 and SLC12A2 genes, which may be involved in schizophrenia pathogenesis." (PMID 22643131, 2012).
diabetic nephropathy (1 paper, 2014). "Therefore, cortexin-3 downregulation in the diabetic kidney might contribute to these two major mechanisms of injury operative in diabetic nephropathy." (PMID 24827579, 2014).
Hypertension (1 paper, 2014). The presence of chronic increased pressure in the systemic arterial system. "Cortexin 3 (Ctxn3, 93% reduction in expression) – originally isolated from goat renal cortex – is a cardioprotective endogenous activator of eNOS that may play a role in the pathogenesis of hypertension." (PMID 24827579, 2014).
neurological disease (1 paper, 2025). "ERRFI1, CTXN3, IRX6, and IQCA1 have not yet been reported in association with neurological disease." (PMID 40944498, 2025).
CTXN3 also shares sentences with these, for which no sentence is quoted: Alzheimer disease (1 paper); deafness (1); dyslexia (1); epilepsy (1); Intellectual disability (1); memory impairment (1).